GFAP (glial fibrillary acidic protein)
Diseases named in the same sentence as GFAP in open-access papers (continued):
Sharing a sentence is not in itself a finding about the gene and the disease.
diabetes (continued). "In agreement with the results shown herein, it has been previously demonstrated that experimental diabetes increases GFAP levels in Müller cells and decreases its expression in astrocytes." (PMID 25004165, 2014). "In SE-housed animals, experimental diabetes provoked a moderate gliosis in Müller cells, as shown by an increase in GFAP-immunoreactivity in these cells, which was prevented by EE housing." (PMID 25004165, 2014). "Reduced co-labeling of GLT-1 and GFAP revealed the altered glutamate transportation in cerebellum following diabetes." (PMID 25400546, 2014). "Increased glial fibrillary acidic protein (GFAP) levels in retinal Müller cells of diabetic animals have been reported within 6–8 weeks of diabetes induction." (PMID 23592917, 2013). "A transient GFAP up-regulation in astrocytes has been reported in STZ-induced diabetic mouse retina at 1 month of diabetes." (PMID 24167638, 2013). "Up-regulation of GFAP in Müller cells has been demonstrated in the retinas of several models of diabetes and of diabetic patients and, as in other forms of pathology, is normally viewed as an indicator of retinal cell stress." (PMID 23408985, 2013). "Caffeine consumption reduced this diabetes-induced astrogliosis, as gauged by the reduction to near control levels of GFAP immunoreactivity and of the number of GFAP-positive cells in the hippocampus." (PMID 22514596, 2012). "In this study, we observed that the retinal expression of GFAP and acute-phase proteins increases in relation to diabetes duration with a pattern similar to that of IL-1β upregulation." (PMID 22615852, 2012). "It has been reported that experimental diabetes in rats induces a differential GFAP expression pattern in the macroglial cells of the retina, reduces GFAP-IR in astrocytes, and increases GFAP-IR in Müller cells." (PMID 22583833, 2012). "Müller glia in both human and experimental diabetes acquire a “reactive” phenotype characterized by cellular hyperplasia and upregulation of glial fibrillary acidic protein (GFAP)." (PMID 21151599, 2010). "Previous studies have shown that after 4 months of STZ-induced diabetes, retinal GFAP is upregulated in Müller glia and relatively downregulated in astrocytes." (PMID 21151599, 2010). "As no prior study has evaluated gfap mRNA levels after combined CUMS+D exposure, we can only speculate that this increase indicates a compensatory response to diabetes distress or reduced GFAP protein expression." (PMID 41462586, 2025). "Increasing levels of plasma NfL and GFAP among older adults with diabetes and overweight or obesity may be indicative of worsening cognition." (PMID 39913137, 2025). "In the Action for Health in Diabetes (Look AHEAD) cohort in overweight/obese subjects with type 2 diabetes (age: 61.4 ± 6.2 years, n = 779) higher alcohol consumption at baseline was associated with higher plasma baseline GFAP levels." (PMID 40082178, 2025). "It is crucial to mention that although GFAP is a widely used molecular marker for reactive astroglia, further investigations should incorporate additional astroglial-specific markers beyond GFAP to obtain a more comprehensive understanding of astroglial responses in diabetes distress." (PMID 41462586, 2025). "The inflammatory response mediated by astrocytes in the diabetic brain may contribute to cognitive decline, highlighting the importance of GFAP in understanding the neuroinflammatory landscape of diabetes." (PMID 39594187, 2024). "Furthermore, diabetes significantly (p < 0.001) increased the number of activated astrocytes by upregulating the immunoexpression of cortical and hippocampal GFAP by 239 and 314.8%, respectively compared to control rats (respectively)." (PMID 38105928, 2023). "In diabetes, it has been well-established that Müller cells become activated early on and one of the most prominent signs of Müller cell activation is the (increased) expression of GFAP, whereas astrocytes precociously undergo cell death by apoptosis." (PMID 37298558, 2023).
diabetes (continued). "The enhanced fluorescent intensity of GFAP in Müller glia fibers and the increased length of the endfeet of Müller glia down to the deep retinal layer indicate the strong activation of Müller glia in diabetic retinae." (PMID 36768614, 2023). "Diabetes induced a significant increase in GFAP+ percent immunoreactive area in CX3CR1-WT (47.64 ± 5.179, 2-way ANOVA P<0.0001) and CX3CR1-KO (49.60 ± 4.794, 2-way ANOVA P<0.0001) mice in comparison to ND controls, (CX3CR1-WT 29.969 ± 3.127 and CX3CR1-KO 30.325 ± 2.976)." (PMID 37033925, 2023). "In the STZ-induced diabetic rats, reactive changes in Müller cells, such as upregulation of GFAP, are observed within 3~4 months of the onset of diabetes while GFAP immunoreactivity in astrocytes is reduced, all of which precede the first signs of obvious vascular changes." (PMID 37174742, 2023). "We have shown for the first time that STZ-induced diabetes can increase the level of GFAP." (PMID 37970441, 2023). "At 4 weeks after injection of STZ, GFAP immunofluorescence was increased, spreading to the outer nuclear layer compared to the normal control group; this trend continued at 12 weeks after induction of diabetes (both p < 0.001)." (PMID 35334819, 2022). "Nicotinamide treatment reduced reactive gliosis in diabetic retinas at 4 and 12 weeks after induction of diabetes (both p < 0.001) in accordance with Guzyk’s study showing that nicotinamide treatment decreased retinal GFAP expression in the retina at 8 weeks after diabetes onset." (PMID 35334819, 2022). "We also used immunoblots to determine whether VEGF and GFAP expression were increased in the retina of a streptozotocin (STZ)-induced rat model of diabetes." (PMID 33479328, 2021). "As expected, many genes merely changed in the sDM group, such as SULF2, GFAP, ABCG1, GCK, ISM1, and CORIN, have been associated with diabetes." (PMID 34880765, 2021). "Müller glia display numerous changes in diabetes, with the most obvious being the induction of gliosis, characterized by cellular hyperplasia and the upregulation of the intermediate filament protein, glial fibrillary acidic protein (GFAP)." (PMID 33679605, 2020). "Immunotherapies employing either whole GFAP or S100-β protect NOD mice from diabetes development." (PMID 30817223, 2019). "With diabetes progression, the expression of GFAP was significantly increased in Müller cells." (PMID 30401898, 2019). "Moreover, immunotherapy with class II I-Ag7– and class I Kd–restricted peptide epitopes derived from GFAP protect NOD mice from diabetes development." (PMID 30817223, 2019). "In addition to morphological measurements, we examined the level of glial fibrillary acidic protein (GFAP), a marker for glial activation associated with neuronal injury and diabetes, in Müller cells." (PMID 31242599, 2019). "The expression of factors such as HIF-1alpha, VEGF, EPO, EPOR, GFAP and vimentin, was up-regulated with the progression of diabetes in the diabetic rat retinas compared to the expression in normal control retinas, whereas the expression of GS and GLAST was down-regulated." (PMID 30401898, 2019). "Furthermore, change of glial fibrillary acidic protein (GFAP) expression has been found in rodent diabetes model." (PMID 30090655, 2018). "To understand the molecular pathology of modified LDL-induced retinal injury in diabetes, we explored alterations in protein markers for glial activation (GFAP), angiogenesis/vascular permeability (VEGF), ER stress (KDEL and p-eIF2α) and apoptosis propensity (BAX) in mouse retina." (PMID 27306616, 2016). "Under sustained stress, as observed in diabetes, the Muller cells produce pro-inflamatory cytokines to restore the retinal homeostasis upregulating glial fibrillary acidic protein (GFAP) and VEGF leading to a glial reaction and blood barrier hyper-permeability." (PMID 26836609, 2016).
diabetes (continued). "This study concluded that insulin injection improved the expression level of the GFAP and NSE genes, but it can be said that insulin injection had different relative effects on gene expression in the brain nuclei due to the degree of disruption caused by diabetes." (PMID 38639646, 2024). "Furthermore, diabetes produced changes in protein expression, measured by Western blot, with an increase in S100β and a decrease in GFAP production, accompanied by a decrease in cells co-expressing S100β and GFAP in the jejunum mucosa, as observed in cryostat sections." (PMID 34205534, 2021). "Furthermore, in addition to vascular disruption we have shown there is significant neuronal impairment (reduced numbers of Brn‐3a + RGC and activation of GFAP + retinal glial) at 6 months, which supports that dysfunction of retinal neurons occurs early following the onset of diabetes." (PMID 32141716, 2020). "Remarkably, ablation of astrocytic Pdk2 in the hypothalamus attenuated diabetes-induced local inflammation, characterized by increased levels of the inflammatory cytokines Tnf-α, Il-1β, and Il-6 mRNA, and proliferation and activation of GFAP-positive astrocytes and Iba-1-positive microglia." (PMID 33219201, 2020). "However, in diabetes an aberrant overexpression of GFAP is shown by Müller cells." (PMID 24837086, 2014). "The time course of GFAP, α2-macroglobulin, and ceruloplasmin overexpression in the retina of diabetic rats was similar to that of IL-1β with no changes as compared to control rats at 1.5 months from the induction of diabetes and a significant upregulation after 3 months of diabetes." (PMID 22615852, 2012). "The diabetes group significantly increased the expression levels of IBA-1 and GFAP in the dorsal and ventral horns after eight weeks of STZ injection compared to the sham group." (PMID 39594606, 2024). "In this study, the expression of GFAP and NSE genes in the affected brain nuclei shows that diabetes has increased the expression of these genes." (PMID 38639646, 2024). "On the other hand, the higher GFAP levels in the young adult Y-DM group, compared to the young adult controls, and the significant increase in GFAP levels in the Y-DM group between adolescence and young adulthood may represent diabetes-related neuroinflammation." (PMID 38764894, 2024). "In our study, diabetes elevated the prefrontal cortex and hippocampal gene expression of NfκB, IL-1β, and IL6, as well as the immunoexpression of TNF-α and GFAP, which are considered indicators of astrocyte activation." (PMID 38105928, 2023). "Diabetes-induced expression of ICAM-1 and GFAP in the retina were attenuated in REDD1−/− mice, as compared to REDD1+/+ mice." (PMID 36309088, 2022). "GFAP, Flt1, 8-OHdG and TNF-ɑ immunoreactivity were increased, and ɑ-SMA, PEDF and SOD3 immunoreactivity were decreased in the diabetic retina." (PMID 35015779, 2022). "The levels of GFAP and the secretion of TNF-α, IL-1β, and IL-6 were significantly increased in the retinas of mice with diabetes compared with those of the mice in the normal group." (PMID 34938383, 2021). "After 42-d treatment (72 d of total duration of diabetes), proinflammatory molecular VEGF-α, GFAP, and Vcam-1 protein expressions were detected by western blot method." (PMID 31396288, 2019). "In order to evaluate the potential anti-inflammatory properties and effect on glial cell reactivity, VEGF-α, GFAP, and VCAM-1 mRNA levels were analyzed by FQ-PCR after 42-d treatment (72 d of total duration of diabetes)." (PMID 31396288, 2019). "Glial fibrillary acidic protein (GFAP) is a marker of AC and known to be up-regulated during diabetes and neuronal damage." (PMID 25068294, 2014). "An increased expression of glial-fibrillary-acidic-protein (GFAP) in the retina and specific abnormalities in the electroretinogram were identified a few weeks after inducing diabetes in animals." (PMID 23587252, 2013).
diabetes (continued). "It provides indications, also for a correlation between serum GFAP levels and small, but not large, nerve fiber affection in people with diabetes." (PMID 40192786, 2025). "There was not any multicollinearity of GFAP levels with age, hypertension, diabetes, baseline NIHSS score, DWI-ASPECTS 0–7, WMLs and hyper-sensitive C-reactive protein levels (all VIF < 10)." (PMID 40421099, 2025). "GFAP expression was reduced in five chronic stress models compared to controls and was increased in one study of CUMS, BDE47 supplementation, diabetes, and finasteride withdrawal, an inhibitor of the enzyme 5α-reductase." (PMID 40485663, 2025). "Overall, from the extant literature on GFAP and NfL in adult diabetes, we interpret our own results as evidence that some neuroinflammation and neuron damage is present and more pronounced in Y-DM and may be a direct result of diabetes." (PMID 38764894, 2024). "Macroglia: Increased GFAP expression was observed in the diabetic non-treated retinas, two weeks after the onset of diabetes." (PMID 38543179, 2024). "However, the levels of GFAP were significantly decreased in samples with AD and a co-occurring ICD-10 code for gastritis and duodenitis or non-insulin dependent diabetes mellitus." (PMID 39371139, 2024). "The only exception was GFAP, which was significantly increased in CU participants with hypercholesterolemia (p = 0.01) and a marginally significant decrease in MCI participants with diabetes (p = 0.5)." (PMID 38755703, 2024). "In agreement with our previous studies, two weeks after the onset of diabetes, a statistically significant increase in the number of activated Iba-1-positive cells and the expression of GFAP protein was observed in the diabetic non-treated retinas." (PMID 38543179, 2024). "The percentage of GFAP+ cells was affected neither by diabetes induction nor by MWCNT treatment, as revealed by the lack of significant effects for the two main factors in the ANOVA." (PMID 36131737, 2021). "Treatment with rapamycin inhibited the diabetes-induced VEGF and GFAP increases." (PMID 33479328, 2021). "Retinal vascular coverage by glial fibrillary acidic protein (GFAP)-labeled astrocyte was evaluated in 3 weeks of STZ-induced diabetes and age-matched non-diabetic control mice." (PMID 26890140, 2016). "In contrast, db/db diabetic mice were reported to show GFAP induction in diabetes, and this glial activation was inhibited in animals lacking aldose reductase." (PMID 21139688, 2010). "Diabetes has not been found to result in upregulation of GFAP in Muller glial cells in retinas of C57Bl/6 mice or Ins2Akita diabetic mice." (PMID 21139688, 2010). "In rodent models of diabetes and high‐fat diet, inulin supplementation did not significantly alter glial markers (GFAP, GDNF) in the colon or brain, nor did it affect myenteric neuronal subpopulations or enteric glial cells, despite reducing inflammation and improving colonic motility." (PMID 41486750, 2026). "Patients with CKD and diabetes had significantly elevated plasma concentrations of NfL (44.8 [36.4–58.6] vs. 32.4 [20.1–43.1] ng/L, p < 0.001) and p-Tau231 (31.7 [24.0–46.6] vs. 23.4 [18.6–32.5] ng/L, p = 0.018), but not of GFAP (207 vs. 187 ng/L, p = 0.10), compared with patients without diabetes." (PMID 40346521, 2025). "Indeed, increased GFAP expression has been detected in brains of different rodent diabetes models, although similar studies have not been performed on human brain samples yet." (PMID 39275164, 2024). "In this study, the application for 8 weeks after diabetes induction of Lactobacillus plantarum combined with the prebiotic fiber inulin (but not alone) improved the composition of the microbiota and reduced the levels of inflammatory cytokines and the expression of GDNF and GFAP." (PMID 34205534, 2021).
diabetes (continued). "The lack of changes in the GFAP protein level cannot be unambiguously connected to the absence of astrocyte participation in the release of this chemokine under diabetes, especially since it was indicated that changes in the level of GFAP are not related to the number of astrocytes." (PMID 29593735, 2018). "In contrast, diabetes did not affect GFAP expression at either 4 or 12 weeks of diabetes (p>0.05)." (PMID 23878504, 2013). "In a cross-sectional design, GFAP and UCH-L1 were measured in 28 persons with diabetes and DPN (DPN+), 31 persons with diabetes without DPN (DPN-) and 30 age- and sex-matched controls." (PMID 40192786, 2025). "Whether the increase in GFAP autoantibody levels in T2D patients reflects elevated plasma GFAP levels or astrocyte activation in the brain is not determined yet, but preclinical studies have shown increased brain GFAP expression in a wide range of different rodent diabetes models." (PMID 39275164, 2024). "In particular, GFAP and AQP4 levels were higher also in diabetic eyes without clinical signs of DR, and they have been suggested as early biomarkers of diabetes-induced retinal stress." (PMID 34216255, 2021). "An increase in glial fibrillary acidic protein (GFAP), for example, is noted in the aqueous humor of patients with diabetes and no signs of DR or with non-proliferative DR compared to age-matched healthy controls." (PMID 29075511, 2017). "However, the expression of the astrocytic marker GFAP and the neuronal activation marker c-fos in the spinal cord dorsal horn of rats with DNP in the early and late phases of diabetes has not been explored previously." (PMID 35799894, 2022). "Summarizing, it seems that GFAP is not influenced by diabetes microvascular complications, as NFL might be, and therefore it stratifies DR from DM more clearly." (PMID 40141267, 2025).